CD4 (CD4 molecule)
Diseases named in the same sentence as CD4 in open-access papers (continued):
Sharing a sentence is not in itself a finding about the gene and the disease.
infection (continued). "Women with infections by more than one high-risk type were notably younger and had lower CD4 lymphocyte counts compared to women with high-risk HPV monoinfection." (PMID 26100400, 2015). "In particular, the model assumes unlimited supply of target cells for virus replication, while several studies have highlighted the spatial heterogeneity of uninfected and infected cells, and the loss of many CD4 T cells during early infection." (PMID 25781919, 2015). "We provide evidence that the loss of surface CD4 is mediated by the Nef and Env proteins in resting cells following direct infection." (PMID 26537682, 2015). "Infections with opportunistic intestinal parasites were associated with lower CD4+ T cell counts in HAART naïve patients only." (PMID 25658626, 2015). "Nonetheless, some investigators report a positive association between CD4+ T-cell counts and infection risk at levels lower than the 500 CD4+ T-cells/mm3 cut-point reported here." (PMID 25794147, 2015). "Following virus transmission, acute/early phase of infection is characterized by high levels of peak viremia, rapid loss of CD4+ T-cells in both peripheral blood and mucosal lymphoid tissues, and in some cases clinical symptoms." (PMID 25093660, 2014). "By contrast, the transfer of Runx3-deficient CD4+ T cells resulted in an exacerbated intestinal inflammation, but provided recipient mice with increased protection against infection with the enteropathogenic bacterium Citrobacter rodentium." (PMID 25339956, 2014). "In contrast to other HIV env mutants that can enter cells via CD4 independent mechanisms, we have discovered an env mutant that is defective in regard to cell-free infection but that can enter some target cells when cell-associated." (PMID 25287969, 2014). "As pDC express the CD4 receptor, they are susceptible to infection by HIV via binding of the gp120 envelope protein of the HIV virion to CD4." (PMID 25505958, 2014). "We observed that developmental exposure to AhR ligands caused lasting changes in CD4+ T-cell responses to infection due to direct effects on the CD4+ T-cell lineage." (PMID 25051576, 2014). "Most importantly, depletion of CD4+ T cells in vaccinated mice resulted in loss of protection, with 100% succumbing to infection upon challenge with wild-type CHIKV, indicating an indispensable role of MVA-CHIK immune CD4+ T cells in protection." (PMID 25058320, 2014). "HIV-infected individuals are at high risk to develop active TB for the progressive CD4 depletion in the first few years after infection, even if the number of peripheral CD4 T cells is still high at the beginning." (PMID 24795723, 2014). "Experimental infection with the myotropic Colombian strain of T. cruzi caused an intense inflammation composed mainly of mononuclear cells (macrophages and CD4+ and CD8+ T cells), which is one of the hallmarks of chronic chagasic cardiomyopathy." (PMID 24984860, 2014). "In vivo we found that HSV-2 latently infected RMs appeared to be more susceptible to vaginal SHIVSF162P3 infection, had higher frequency of α4β7high CD4+ T cells in the vaginal tissue and higher expression of α4β7 and CD11c on vaginal DCs." (PMID 25521298, 2014). "It is well known that HCV and HIV CD8+ and CD4+ T cell epitopes mutate over the course of infection, decreasing MHC binding as a mechanism of viral escape." (PMID 25339942, 2014). "The variant H186R of A3G is also associated with low CD4 counts and a polymorphism within an A3G intron (C40693T) was shown to correlate with increased risk of infection." (PMID 25352838, 2014). "This has since been attributed to the ability of B cells to produce specific antibodies, as passive transfer of immune serum or anti-Chlamydia antibodies into B cell-deficient, CD4+ depleted mice rescues their ability to clear a secondary infection." (PMID 25386180, 2014).
infection (continued). "In the dose de-escalation CPS-immunization cohort, we have recently shown that sterile protection from challenge infection was associated with induction of higher levels of CD4+ T-cells with a cytotoxic phenotype (CD107a+)." (PMID 24970846, 2014). "In fact, all control macaques suffered a profound CD4+ T cell loss (<518 CD4+/mmc) in the acute phase of infection, due to the robust viral replication, and two of them (AC032 and AC739) died at weeks 40 and 46, respectively." (PMID 25356594, 2014). "When immune CD4+ T-cells were depleted, despite the presence of full levels of circulating anti-virus antibodies, mice were 100% susceptible to lethal infection." (PMID 25058320, 2014). "As the findings of logistic regression showed, the perceived social support, gender, CD4 cell counts and route of transmission of infection had significantly associated with the disclosure of HIV-status after adjustment for other variables in the model." (PMID 25389470, 2014). "A critical difference between non-pathogenic SIV infection (sooty mangabeys, African green monkeys) and pathogenic infection (rhesus macaques, pig-tailed macaques) is in preservation of CD4+ Th17 cells in the sooty mangabeys and African Green monkeys." (PMID 25161656, 2014). "The aims were to describe the spectrum of infections, to determine their prevalence and to assess their associations with diarrhea, CD4 cell count, place of residence and living conditions." (PMID 24662743, 2014). "In this study, we demonstrated that the infection of primary CD4+ T cells with either CXCR4-tropic HIV-1NL4-3 or CCR5-tropic HIV-1YU2 causes CD4+ T cell depletion by both necroptosis and apoptosis." (PMID 24714696, 2014). "Our previous studies demonstrated that cytolytic CD4 T cells differentiate in vivo following infection with highly pathogenic IAV, PR8 (H1N1)." (PMID 24586481, 2014). "We first sought to determine if the infection of CD4+ T cells with HIV-1 causes changes in flux through the glycolytic pathway and the TCA cycle." (PMID 25421745, 2014). "We found a significant association between the turnover of SIV DNA in resting CD4 T cells and the timing of escape – when escape occurred early in infection, there was a faster turnover of SIV DNA in resting CD4 T cells." (PMID 24710023, 2014). "In that study, 30% of mice depleted of CD4+ T cells succumbed to neurologic disease following ΔNSs infection, in association with reduced antibody titers and evidence of altered CD4+ T cell regulatory function." (PMID 24922480, 2014). "The most likely explanation is that the protective antibodies generated during infection/cure need CD4+ T cell help, which is lost in CD4+ T cell deficient animals." (PMID 24620841, 2014). "The higher tolerance of individuals, who contracted HIV at a young age, is likely to be explained by the higher thymic output of young individuals that can compensate infection-related CD4+ T-cell loss." (PMID 25226169, 2014). "The normalization of the cell-associated SHIV-DNA level to the CD4+ T-cells counts suggest a decrease in the frequency of infection of these cells post-transplant." (PMID 25254512, 2014). "This induced severe thymic atrophy that is evident 10 days post-infection, is mainly due to the CD4+CD8+ double positive loss." (PMID 25330249, 2014). "Failure to resolve infection was associated with reduced production of Th2 cytokines, particularly IL-13 and IL-4, abrogated humoral immunity and failure to expand the memory CD4+ T cell compartment." (PMID 24516382, 2014). "CRAMP-deficient mice had a greater expansion of splenic CD4+ T cells at late time-points of infection when compared to control animals and also showed increased numbers of B cells, myeloid CD11b+ cells and regulatory (CD4+CD25+FoxP3+) T cells." (PMID 25400920, 2014). "A third study reported that CD4+ T cells from EC were as susceptible to infection as CD4+ T cells from uninfected individuals." (PMID 23577012, 2013).
infection (continued). "Infection of mice that lack CD4 T cells either by antibody depletion or genetic deficiencies in CD4 or class II MHC results in enhanced disease and mortality." (PMID 24153060, 2013). "Other highly susceptible cells, such as CD4+ T cells, are recruited to these infectious clusters promoting infection dissemination and systemic spread." (PMID 24369910, 2013). "On the other hand, the role of different CD4+ T cell subsets has been reported in experimental T. cruzi infection in mice, but always utilizing susceptible host models of infection." (PMID 23776551, 2013). "Even though the CD4+ T cells in LAINefP72A/P75A infected mice were nearly depleted, we continued monitoring the infection past eight weeks to determine if further mutations would occur during LAINefP72A/P75A infection." (PMID 24172637, 2013). "Accordingly, parasites co-inoculated with saliva (SGE-1X) caused an increase in the recruitment of CD4+Foxp3+ cells to the infection site, suggesting that saliva of L. longipalpis increases Tregs during the infection." (PMID 23656976, 2013). "In these animals, activation of macrophages and CD4 T cells peaks by 4 weeks and gradually declines by 12 weeks post-infection, in association with resolution of the pathology and clearance of bacilli from the lungs." (PMID 23448601, 2013). "In contrast, CD4+ naïve T cells (Tn) are more susceptible to trans infection with X4 virus in relation to expression of CXCR4." (PMID 24278768, 2013). "The iron-induced oxidative burst elicited during both primary and secondary infections with L. major is linked to the activation of the transcription factor NF-κB and with an enhanced proliferation of IFNγ-secreting CD4+ T cells in the draining lymph nodes." (PMID 24367768, 2013). "Infections with opportunistic intestinal parasite were associated with lower CD4 counts in ART naïve patients only." (PMID 23442332, 2013). "Over the time course after infection TGF-β1 expression was correlated with CD4/CD8 T-cell ratio long described as a hallmark of AE severity." (PMID 23405141, 2013). "The cis infection process requires CD4, which is more efficient via cell associated virus and can be enhanced by virus opsonized with antibody and complement, while blocked by IgG alone via binding to FCγR." (PMID 24278768, 2013). "Cryptococcus neoformans and Penicillium marneffei, both of which can be lethal to HIV-1 infected persons, enhance DC-mediated HIV-1 trans infection in association with increases in DC-T cell conjugates and CD4+ T cell activation." (PMID 24278768, 2013). "IFN-γ-deficient mice receiving immune CD4+ lymphocytes from vaccinated, wild type donor mice displayed improved survival after infections." (PMID 24324681, 2013). "The CCR5 Δ32 mutation abrogates infection of CD4+ T-cells by R5 HIV-1 viruses, the strains most frequently associated with early stage infection and which are transmitted preferentially between individuals." (PMID 23364195, 2013). "CSP-specific CD4+ T cells have been associated with protection from infection in RTS,S vaccinated children and in children with naturally-acquired immunity." (PMID 23613845, 2013). "The infection of T-cell lines and primary CD4+ T cells with HIV was initially reported to be associated with stronger expression of pro-apoptotic genes, such as those encoding Bax, p21 and MDM2." (PMID 23658518, 2013). "One such molecule, bile-salt stimulated lipase (BSSL) from milk, is highly polymorphic with the variant forms differentially inhibiting viral capture and infection of CD4+ lymphocytes." (PMID 23874931, 2013). "We investigated the effect of Nox1−/y deficiency on the number and functionality of CD8+ and CD4+ T cells and of T regulatory cells at Day 7 post infection." (PMID 23577160, 2013). "While the RSV-specific T cell response plays a major role in viral clearance and the clinical outcome of infection, both Th2-biased CD4+ and CD8+ T cells have been implicated in immunopathogenesis." (PMID 23947615, 2013).
infection (continued). "More attention has been paid to immunological effects of long-term FIV infection, with a particular emphasis on the hallmark CD4+ T-cell depletion and persistent CD4/CD8 ratio inversion." (PMID 23829177, 2013). "A similar phenomenon has been observed for HIV, which causes down modulation of the receptor CD4 following infection." (PMID 23460925, 2013). "Protection against EAAI to OVA was stronger during the chronic phase of infection and associated with increased numbers of splenic CD4+CD25+Foxp3+ Treg cells with suppressive activity." (PMID 23365718, 2013). "The precise mechanism by which CD4+ T-cells cause EEC hyperplasia during infection remains to be elucidated." (PMID 23349631, 2013). "We have identified factors associated with delayed wound healing - post-operative infection, tight sutures, and low CD4 counts in ARV-naive HIV-positive patients - that should be taken into account in training for and implementing VMMC programs." (PMID 23613918, 2013). "The dramatic and near complete loss of peripheral CD4 T cells is typical of infection of macaques with CXCR4-utilizing SHIV strains." (PMID 23460840, 2013). "The ensuing DC maturation enhances susceptibility of CD4+ T cells to productive infection with HIV-1." (PMID 23844079, 2013). "Although CD4+CD25+ T cells have been identified as critical regulators of immune response during infections caused by different protozoa, their role in regulating the outcome of T. cruzi infection is not clear." (PMID 23509755, 2013). "Here target cells correspond mostly to CD4+ T cells expressing an appropriate co-receptor so as to be susceptible to infection." (PMID 24020860, 2013). "Previously we reportedthat the onset of CD4+CD8+ cell loss occurs after 8 dayspost-infection (dpi), and is characterized by the increase in the percentage of apoptosis." (PMID 24324845, 2013). "The hallmark of infection with H. pylori is chronic active gastritis comprised of polymorphonuclear leukocytes together with Th1, Th17, and Treg CD4+ lymphocytes." (PMID 23468628, 2013). "Expression of either MIP1α or CD4 individually provided significant protection from infection with several variants of HIV-1 pseudovirus representing clade B in a standard single cycle infection assay." (PMID 23840383, 2013). "These chemokines induce neither CD69 nor CD25 expression, but do increase the susceptibility of resting CD4+ T cells to infection by a replication-competent HIV-1 virus." (PMID 23803414, 2013). "We previously observed that systemic loss of human CD4+ T cells from organs closely paralleled loss of human CD4+ T cells from blood during infection with wild type (LAI) and nef-defective (LAINefdd) virus." (PMID 24172637, 2013). "Prior work had described successful protection from infection with HIV-1 pseudovirus representing clade B provided by MIP1α or CD4 encoded bacteria." (PMID 23840383, 2013). "Here we provide evidence that induction of schistosome-specific CD4+ T cell responses by pre-patent infection is accompanied by loss of CD4+ T cell responsiveness to non-schistosome antigens." (PMID 23556020, 2013). "After orally infection with S. Typhimurium, the mice injected with an anti-CD4 antibody demonstrated accelerated weight loss and increased mortality compared to mice injected with an isotype control." (PMID 23750260, 2013). "This includes activated primary human CD4+ T cells, which became susceptible to infection only under co-culture conditions." (PMID 23308151, 2013). "It has been recently shown that in these patients HBV viremia, in cases of occult infection, is significantly associated with lower CD4 counts." (PMID 22829332, 2013). "Nevertheless, such virus-carrying iDCs can facilitate HIV-1 spreading through cis-infection (i.e. direct infection) of susceptible effector CCR5+ CD4+ T cells located deeply within the mucosa." (PMID 23844079, 2013).
infection (continued). "The selective loss of Th17 CD4+ T cells from the gut – possibly due to selective infection – has therefore been held responsible for the long-term loss of the intestinal integrity and thereby for chronic immune activation in pathogenic HIV infection." (PMID 24133492, 2013). "Different studies recently reported that among HIV-1 group M subtypes, infection with subtype D is associated with a significantly faster CD4 cell decline than other subtypes, thus indicating an increased pathogenicity of subtype D viruses." (PMID 22529893, 2012). "Evidences come from studies showing the inability of animals deficient in B or CD4+ T cells to effectively control and clear the infection." (PMID 22229039, 2012). "Repeated rounds of infection of susceptible CD4+ cells of various types occur with continued generation of long-lived cells harboring replication competent virus, and that persist during therapy." (PMID 22319447, 2012). "In this study, by 6 weeks post-infection, the viral setpoint was reached and animals were already exhibiting a mean 33% loss in CD4 counts relative to baseline levels." (PMID 22442716, 2012). "Immature CD4+CD8+ DP thymocytes were most susceptible to infection, with about 12.8% of CD3− DP, 23.2% of CD3lo DP and 23% of CD3hi DP cells positive for N protein compared to 3.28% of CD4+ SP or 1.36% of CD8+ SP cells." (PMID 23029357, 2012). "Direct infection of CD4+ T cells in the gut-associated lymphoid tissue triggers profound alterations in mucosal immunity." (PMID 23209754, 2012). "This has been associated with the killing of CD4+ cells in the granuloma, probably resulting in a direct disruption of granuloma structure and abolition of the containment of infection." (PMID 22363214, 2012). "TDR was positively associated with the MSM transmission route, subtype B infection and negatively associated with CD4 cell counts." (PMID 22448246, 2012). "To answer this question, we studied a subset of the linked recipients (n = 63) for whom CD4+ T cell counts were available at regular three month intervals for greater than one year post-infection." (PMID 23209412, 2012). "The hallmark of infection is characterised by progressive depletion of CD4+ T-cells leading to an immunodeficiency state, paving the way for opportunistic infection and ultimately mortality." (PMID 24278714, 2012). "Since the expression level of LFA-1 and ICAM-1 in effector/memory CD4 T-cells is higher than that in naïve CD4 T cells, effector/memory CD4 T cells are likely to be more susceptible to de novo cell-to-cell infection than naïve CD4 T cells." (PMID 23198153, 2012). "Although virus infection can be detected in different tissues in these animals, the loss of CD4 cells seems inconsistent with direct infection owing to the relatively few infected cells seen by histopathology." (PMID 23202514, 2012). "The gastrointestinal tract is a privileged site for both HIV-1/SIV replication and extensive CD4+ T-cell depletion at all stages of the pathogenic infection." (PMID 22632376, 2012). "HIV, which is usually transmitted through unprotected sex, destroys CD4 lymphocytes and other immune system cells, leaving infected individuals susceptible to other infections." (PMID 22802730, 2012). "R5 HIV-1 was predominant in TN individuals with HIV-1 subtypes C, A, and D and TE individuals with subtypes C and A. Higher CD4+ count correlated with R5 prevalence, while treatment experience was associated with increased non-R5 infection in all subtypes." (PMID 22281097, 2012). "Infection was also associated with emergence of a population of splenic CD3ε+CD4+ T cells capable of producing both IFNγ and IL-10." (PMID 22911108, 2012). "Although CrNA was associated with overall lower CD4 T cell levels prior to infection and during acute infection, there was a positive association with the fraction of CD4 T cells expressing high levels of PD-1." (PMID 22833745, 2012).